VDR (vitamin D receptor)
Diseases named in the same sentence as VDR in open-access papers (continued):
Sharing a sentence is not in itself a finding about the gene and the disease.
multiple sclerosis (38 papers, 2009 to 2025). A progressive autoimmune disorder affecting the central nervous system resulting in demyelination. "To address this issue, we conducted a case-control study to clarify the impact of four specific VDR genetic polymorphisms in individuals from Jordan affected by multiple sclerosis (MS)." (PMID 40961116, 2025). "We aimed to examine the genetic associations between polymorphisms in the VDR gene (specifically, TaqI, BsmI, ApaI, and FokI) and susceptibility to Multiple Sclerosis (MS)." (PMID 40961116, 2025). "First, it is among the few investigations to examine the association between VDR gene polymorphisms (FokI and ApaI) and multiple sclerosis susceptibility in a Middle Eastern population, addressing an underrepresented demographic in genetic MS research." (PMID 40961116, 2025). "Numerous investigations have explored the relationship between polymorphisms within the VDR gene and susceptibility to Multiple Sclerosis." (PMID 40961116, 2025). "The genotype frequencies of the FokI SNP (rs2228570(T/C)), located proximal to the translation initiation codon within exon number 2 of the Vitamin D Receptor gene on chromosome 12, demonstrated an association with susceptibility to Multiple Sclerosis (MS)." (PMID 40961116, 2025). "Association between different VDR SNP genotypes and multiple sclerosis (MS) clinical characteristics." (PMID 40961116, 2025). "Our study addresses this gap by examining VDR polymorphisms in relation to multiple sclerosis susceptibility in a region where such data remain scarce." (PMID 40961116, 2025). "1,25(OH)2D3 and its receptor also play a pivotal role in multiple sclerosis (MS), as low levels of 1,25(OH)2D3 and the circulating form of 25-hydroxyvitamin D3 (25(OH)D3) or alterations in the VDR gene are a risk factor for this condition." (PMID 38203278, 2023). "The association between the Vitamin D Receptor (VDR) gene polymorphism and the risk of Multiple sclerosis (MS) has been evaluated in several researches." (PMID 31878897, 2019). "SNPs rs731236 and rs1544410 in the VDR gene were associated with risk of multiple sclerosis in Mexican and Kuwaiti studies." (PMID 29581796, 2018). "An alternative promoter of the VDR gene shows altered DNA methylation levels in patients with multiple sclerosis, and it is associated with VDR mRNA upregulation." (PMID 28355272, 2017). "While the VDR gene exhibits over 30 identified polymorphisms, these genetic variations could form a genetic basis for susceptibility to Multiple Sclerosis (MS), providing valuable insights into the relationship between Vitamin D and MS." (PMID 40961116, 2025). "Multiple sclerosis (MS) is a common disease of the central nervous system.This disease may be initiated by either vitamin deficiency or triggered by abnormality inCYP24A1 and vitamin D receptor." (PMID 28836398, 2017). "This study aimed to investigate the association between vitamin D receptor (VDR) gene polymorphisms—specifically Fok-I (rs2228570) and Apa-I (rs7975232)—and the susceptibility to multiple sclerosis (MS) in a Jordanian cohort." (PMID 40961116, 2025). "Vitamin D and VDR are recognized as both environmental and genetic factors in the etiopathogenesis of neurodegenerative diseases such as Multiple Sclerosis (MS), Parkinson’s Disease (PD), Alzheimer’s Disease (AD), and Amyotrophic Lateral Sclerosis (ALS)." (PMID 40464816, 2025). "Changes in methylation of VDR were found in many diseases, like cancer, infectious diseases, immune disease, multiple sclerosis, and kidney stones." (PMID 36246903, 2022). "VDR promoter at exon 1c showed increased DNA methylation levels in T cells from patients with multiple sclerosis compared to controls, with 6.5-fold increase in VDR mRNA levels." (PMID 36246903, 2022). "In turn, the TaqI polymorphism is involved in the regulation of the stability of VDR mRNA, and the TT genotype modulates VDR expression and confers protection against multiple sclerosis." (PMID 32727130, 2020).
multiple sclerosis (continued). "Poor VD status and genetic variations of vitamin D receptor (VDR) are implicated in the pathogenesis of a number of neuropsychiatric disorders including Alzheimer’s disease, depression and multiple sclerosis." (PMID 26528998, 2015). "Vitamin D3 Receptor (VDR) genotype and allelic variants of patients with multiple sclerosis (MS) and healthy volunteers." (PMID 23840333, 2013). "Furthermore, while differences in CYP27B1 and VDR expression have been documented in autoimmune and chronic inflammatory diseases such as multiple sclerosis and cancer, direct transcriptomic evidence in RA remains scarce." (PMID 40870018, 2025). "Notably, the SNPs (Fok-I, p-value = 0.03) and (Apa-I, p-value = 0.04) within the Vitamin D Receptor gene are correlated with an elevated likelihood of developing multiple sclerosis." (PMID 40961116, 2025). "Although evidence exists for a causal association between 25-hydroxyvitamin D (25(OH)D) serum levels, and multiple sclerosis (MS), the role of variation in vitamin D receptor (VDR) binding in MS is unknown." (PMID 38346204, 2024). "Moreover, decreased VDR mRNA levels were detected in the peripheral blood mononuclear cells of vitamin D supplemented multiple sclerosis patients." (PMID 31509973, 2019). "To begin to ask whether DNA methylation within vitamin D receptor (VDR) gene is altered in multiple sclerosis (MS), we examined the main promoter of VDR by bisulfite cloning sequencing." (PMID 28355272, 2017). "In contrast to previous studies that identified microglia/macrophages as the primary sources of CXCL10 in multiple sclerosis patients, we detect evident CXCL10 expression primarily in ECs, but not in VDR-deficient microglia/macrophages in the ischemic brain." (PMID 36890539, 2023). "UV-B phototherapy is also used in the treatment of Multiple Sclerosis and has been found to prevent multiple sclerosis like symptoms in a mouse model regardless of the presence of vitamin D or the vitamin D receptor." (PMID 35359420, 2022). "SNPs rs7975232, rs731236, and rs1544410 in the VDR gene are not a predictor for disease disability progression rate in multiple sclerosis in Slovaks." (PMID 29581796, 2018).
Autoimmunity (36 papers, 2009 to 2024). The occurrence of an immune reaction against the organism's own cells or tissues. "Polymorphisms in the vitamin D receptor (VDR) gene are linked to autoimmunity and an increased risk of infectious diseases, particularly affecting human intestinal T cells and enhancing type 1 immune responses." (PMID 38594256, 2024). "The presence of particular VDR SNP alleles and genotypes, thus, was observed to modulate the likelihood of developing diverse autoimmune conditions, either increasing or reducing it." (PMID 37508347, 2023). "Reduction in VDR in neurons during early life made mice more susceptible to EAE, indicating that VDR signaling in neurons is somewhat protective to CNS autoimmunity." (PMID 32082243, 2020). "Polymorphisms of vitamin D receptor (VDR) contribute to the pathogenesis of multiple autoimmune conditions." (PMID 28426778, 2017). "Another line of evidence that indicates a role for vitamin D in human autoimmunity is the correlation with polymorphisms in the VDR." (PMID 28163705, 2016). "In this review, we summarize and discuss data analyzing the possible involvement of the four best studied VDR gene polymorphisms in the pathogenesis of autoimmune conditions, with the aim of better understanding these mechanisms and shedding light on what needs to be further investigated." (PMID 37508347, 2023). "Both children or maternal VDR SNPs may lower VDR expression and, by consequence, inhibit T-cell proliferation, and increasing risk of autoimmunity." (PMID 34940947, 2021). "Moreover, there is an association between certain VDR polymorphisms and autoimmunity as VDR FokI and TaqI polymorphisms are associated with an increased risk in SLE and RA." (PMID 32353972, 2020). "To more directly address the question as to whether neuron-specific vitamin D signaling in early life is playing a role in the risk of developing CNS autoimmunity, we utilized mice that have an inducible and conditional reduction in VDR in neurons." (PMID 32082243, 2020). "It is postulated that different polymorphic variants of VDR, through their effect on receptor structure or expression, could influence the risk of autoimmune disorders." (PMID 31531369, 2019). "The impact of VDR SNPs on predisposition to autoimmunity may also vary depending on studied population or ethnicity." (PMID 31531369, 2019). "It was suggested that the change in the VDR structure may alter the biological function of VDR-vitamin D transcriptional signaling and may contribute to carcinogenesis, autoimmunity and susceptibility to infectious diseases, including viral hepatitis." (PMID 31864292, 2019). "Another piece of evidence that suggests a potential role of vitamin D in the immune system and the mediation of autoimmune diseases is that a few well-described VDR polymorphisms, namely, ApaI, FokI, BsmI, and TaqI, were demonstrated to be associated with the risk of the development of autoimmunity." (PMID 30103428, 2018). "The vitamin D receptor (VDR) is a ligand-activated transcription factor, and recent analysis of VDR genome-wide occupancy using ChIP-seq revealed that loci associated by GWAS in several autoimmune conditions including IRF8 (associated with MS) and PTPN2 (Crohn's disease and T1D) were bound by VDR." (PMID 23122694, 2013). "In vivo studies of VDR-KO mice found high levels of mature DCs and abnormal DC chemotaxis, highlighting the importance of vitamin D-VDR in self-tolerance development and autoimmunity." (PMID 36831641, 2023). "In this work, we will review the scientific literature suggesting a role for these different factors in the pathogenesis of autoimmune conditions and summarize evidence indicating a possible VDR SNP involvement in the onset of these diseases." (PMID 37508347, 2023). "Partial deletion of VDR in neurons during early life resulted in exacerbated CNS autoimmunity in adult mice." (PMID 32082243, 2020).
Autoimmunity (continued). "Vitamin D and VDR signaling together have a suppressive role on autoimmunity and an anti-inflammatory effect, promoting dendritic cell and regulatory T-cell differentiation and reducing T helper Th 17 cell response and inflammatory cytokines secretion." (PMID 30400332, 2018). "There is a complex interaction between vitamin D and polymorphisms of the vitamin D receptor (VDR) and both the risk of autoimmunity and the responsiveness to vitamin D supplementation." (PMID 24739187, 2014). "Along this line Hayes and coworkers developed a mouse model in which only the T cells included an inactive VDR gene in order to investigate the implication of T cells in development of autoimmunity." (PMID 23785369, 2013). "Altogether, these observations emphasize a role for VDR expression in development and progression of autoimmunity." (PMID 23785369, 2013). "Vitamin D via the VDR has a role in immune regulation and vitamin D analogues are well-established therapies for some autoimmune conditions such as psoriasis." (PMID 23778150, 2013). "A better understanding of the role of the molecular mechanisms linking Vitamin D/VDR and autoimmunity might be extremely useful in designing novel therapeutic avenues for these disorders." (PMID 37508347, 2023). "It was previously proposed that the main mechanism by which VDR activation affected autoimmunity was through genetic activation of myeloid immune cells, particularly antigen-presenting dendritic cells (DCs), thereby triggering a tolerance status in the immune system, particularly in DCs." (PMID 36211484, 2022). "While vitamin D has been shown to reduce the production of lupus-related autoantibodies, such as anti-nuclear antibody (ANA), independent of its impact on B cell differentiation, VDR binds to the IL-10 promotor and enhances IL-10 production, potentially alleviating autoimmunity." (PMID 30103428, 2018). "However, the role played by vitamin D in inflammatory response and autoimmunity appears to be more substantial in Th2 and Th17 than in Th1 cells, partly due to the low expression of VDR in the latter." (PMID 30103428, 2018). "Similar to the VDR, other nuclear receptors, such as the aryl hydrocarbon receptor, also regulate intestinal microbiome, enhance barrier integrity, reduce inflammation and autoimmunity, and increases disease tolerance." (PMID 30828578, 2018). "The VDR also seems to be crucial for proper development of invariant natural killer (iNK) cells, a subset of lymphoid cells involved in the most basic immune responses and also in restricting autoimmunity." (PMID 23778150, 2013). "VDR activation, shown to protect renal function, operates through a multitude of mechanisms: it suppresses the renin-angiotensin system, reduces inflammation, inhibits fibrogenesis, enhances mitochondrial function, attenuates autoimmunity, and reduces renal cell apoptosis." (PMID 38318147, 2024). "The vital role of vitamin D and microbiota in immune responses, including autoimmunity, SOCS1, and SOCS3, have been reported to be involved in Vitamin D metabolism through the VDR-miRNA155-SOCS1 pathway, negatively regulating inflammation and disease pathogenesis." (PMID 38006062, 2023). "Since CD8+ T cells have a higher expression of VDR than CD4+ T cells, CD8+ T cells may also be a target for 1,25(OH)2D3 in the suppression of autoimmunity." (PMID 28163705, 2016). "It has been postulated that low 25(OH)D3 is the result of VDR dysfunction and not the reason for autoimmunity." (PMID 26316435, 2015). "Since the vitamin D receptor (VDR) is expressed in many cell types, this study investigated an alternative hypothesis—neuron-specific VDR signaling induces anti-inflammatory molecules that protect the central nervous system from autoimmunity." (PMID 32082243, 2020).
sarcopenia (36 papers, 2012 to 2025). Progressive decline in muscle mass due to aging which results in decreased functional capacity of muscles. "Studies to date have explored the relationship between Single Nucleotide Polymorphisms (SNPs) and sarcopenia, focusing on vitamin D receptor (VDR), interleukin-6 (IL6), alpha-actinin-3 (ACTN3), and Myostatin (MSTN) polymorphisms." (PMID 40772803, 2025). "The VDR plays a pivotal role in maintaining skeletal muscle homeostasis and is essential for vitamin D uptake by muscle cells, while a decrease in the VDR level is associated with sarcopenia." (PMID 38627219, 2024). "The onset of sarcopenia is associated with a decline in vitamin D receptor (VDR) expression, wherein reduced VDR levels contribute to muscle atrophy, while heightened expression promotes muscle hypertrophy." (PMID 38004107, 2023). "Meanwhile, the hypermethylation of the VDR promoter region in the sarcopenic group has been confirmed by comparing differences in DNA methylation associated with sarcopenia in blood samples from control and elderly women with sarcopenia." (PMID 37881635, 2023). "To date, five studies have investigated the association of SNPs with sarcopenia; limited to VDR, IL6, ACTN3 and MSTN polymorphisms." (PMID 32076017, 2020). "Further studies with larger sample size are needed to verify the relationship of VDR gene polymorphisms with sarcopenia." (PMID 32696506, 2020). "Here, in this study, we studied the relationship of VDR gene polymorphism with muscle traits (muscle mass, muscle strength, and physical performance) and sarcopenia." (PMID 32696506, 2020). "To date, studies focusing on genes associated with sarcopenia itself are rare; only the influences of the genetic variants of Alpha-actinin-3, Caveolin-1 and vitamin D receptor were investigated in connection with sarcopenia so far." (PMID 33505434, 2020). "In this study, we explored the association between the gene polymorphism of Bsm1 and Fok1 of VDR and sarcopenia, as well as muscle trait." (PMID 32696506, 2020). "In this study, the relationship of VDR gene polymorphism with muscle traits (muscle mass, muscle strength, and physical performance) and sarcopenia were studied in Xinjiang, China." (PMID 32696506, 2020). "From genetic point of view, we showed a putative association among polymorphisms FokI and Cdx2 of VDR gene, vitamin d receptor activation and the occurrence of sarcopenia." (PMID 30574409, 2018). "Genetic polymorphisms in the vitamin D receptor (VDR) have been linked to sarcopenia occurrence and supplementation of vitamin D decreases the rate of falls among older adults." (PMID 25097722, 2014). "Previous research has focused on the correlation between VDR polymorphisms, muscle mass, and sarcopenia in elderly and found that individuals with the FokI GG genotype were more likely to have a lower muscle mass and to develop sarcopenia than AA and AG genotypes." (PMID 39330730, 2024). "The results of this study demonstrate that GG allelic variations in CYP2R1 (rs10741657), GC (rs2282679) and VDR (rs2228570) genes affect a patient’s vitamin D sufficiency status that may increase the risk of sarcopenia." (PMID 36233147, 2022). "Furthermore, it has also been reported that the polymorphism of VDR gene is associated with sarcopenia." (PMID 34350631, 2021). "Little research has been done on VDR gene polymorphisms and sarcopenia." (PMID 32696506, 2020). "Taken together, these results could indicate that genetic variation in VDR has a modest influence on lower muscle strength and risk of sarcopenia." (PMID 33505434, 2020). "The association between VDR gene polymorphism and sarcopenia is less reported." (PMID 32696506, 2020). "Moreover, given that VDR variation has a moderate effect on sarcopenia risk, a larger sample size of probably one hundred cases would be required to detect a significant association." (PMID 33505434, 2020).